SRC (SRC proto-oncogene, non-receptor tyrosine kinase)
Description:
Non-receptor protein tyrosine kinase which is activated following engagement of many different classes of cellular receptors including immune response receptors, integrins and other adhesion receptors, receptor protein tyrosine kinases, G protein-coupled receptors as well as cytokine receptors. Participates in signaling pathways that control a diverse spectrum of biological activities including gene transcription, immune response, cell adhesion, cell cycle progression, apoptosis, migration, and transformation. Due to functional redundancy between members of the SRC kinase family, identification of the specific role of each SRC kinase is very difficult. SRC appears to be one of the primary kinases activated following engagement of receptors and plays a role in the activation of other protein tyrosine kinase (PTK) families. Receptor clustering or dimerization leads to recruitment of SRC to the receptor complexes where it phosphorylates the tyrosine residues within the receptor cytoplasmic domains. Plays an important role in the regulation of cytoskeletal organization through phosphorylation of specific substrates such as AFAP1. Phosphorylation of AFAP1 allows the SRC SH2 domain to bind AFAP1 and to localize to actin filaments. Cytoskeletal reorganization is also controlled through the phosphorylation of cortactin (CTTN) (Probable). When cells adhere via focal adhesions to the extracellular matrix, signals are transmitted by integrins into the cell resulting in tyrosine phosphorylation of a number of focal adhesion proteins, including PTK2/FAK1 and paxillin (PXN). In addition to phosphorylating focal adhesion proteins, SRC is also active at the sites of cell-cell contact adherens junctions and phosphorylates substrates such as beta-catenin (CTNNB1), delta-catenin (CTNND1), and plakoglobin (JUP). Another type of cell-cell junction, the gap junction, is also a target for SRC, which phosphorylates connexin-43 (GJA1). SRC is implicated in regulation of pre-mRNA-processing and phosphorylates RNA-binding proteins such as KHDRBS1 (Probable). Phosphorylates PKP3 at 'Tyr-195' in response to reactive oxygen species, which may cause the release of PKP3 from desmosome cell junctions into the cytoplasm. Also plays a role in PDGF-mediated tyrosine phosphorylation of both STAT1 and STAT3, leading to increased DNA binding activity of these transcription factors (By similarity). Involved in the RAS pathway through phosphorylation of RASA1 and RASGRF1. Plays a role in EGF-mediated calcium-activated chloride channel activation. Required for epidermal growth factor receptor (EGFR) internalization through phosphorylation of clathrin heavy chain (CLTC and CLTCL1) at 'Tyr-1477'. Involved in beta-arrestin (ARRB1 and ARRB2) desensitization through phosphorylation and activation of GRK2, leading to beta-arrestin phosphorylation and internalization. Has a critical role in the stimulation of the CDK20/MAPK3 mitogen-activated protein kinase cascade by epidermal growth factor (Probable). Might be involved not only in mediating the transduction of mitogenic signals at the level of the plasma membrane but also in controlling progression through the cell cycle via interaction with regulatory proteins in the nucleus. Plays an important role in osteoclastic bone resorption in conjunction with PTK2B/PYK2. Both the formation of a SRC-PTK2B/PYK2 complex and SRC kinase activity are necessary for this function. Recruited to activated integrins by PTK2B/PYK2, thereby phosphorylating CBL, which in turn induces the activation and recruitment of phosphatidylinositol 3-kinase to the cell membrane in a signaling pathway that is critical for osteoclast function. Upon activation of the G(q)- dependent KISS1/KISS1R signaling pathway, active SRC is recruited, together with the phosphatase DUSP18, to the KISS1R C-terminus. This leads to DUSP18-mediated SRC dephosphorylation and inactivation, down-regulation of osteoclast differentiation and activity, and consequently suppression of bone resorption (By similarity). Promotes energy production in osteoclasts by activating mitochondrial cytochrome C oxidase. Phosphorylates DDR2 on tyrosine residues, thereby promoting its subsequent autophosphorylation. Phosphorylates RUNX3 and COX2 on tyrosine residues, TNK2 on 'Tyr-284' and CBL on 'Tyr-731'. Enhances RIGI-elicited antiviral signaling. Phosphorylates PDPK1 at 'Tyr-9', 'Tyr-373' and 'Tyr-376'. Phosphorylates BCAR1 at 'Tyr-128'. Phosphorylates CBLC at multiple tyrosine residues, phosphorylation at 'Tyr-341' activates CBLC E3 activity. Phosphorylates synaptic vesicle protein synaptophysin (SYP) (By similarity). Involved in anchorage-independent cell growth. Required for podosome formation (By similarity). Mediates IL6 signaling by activating YAP1-NOTCH pathway to induce inflammation-induced epithelial regeneration. Phosphorylates OTUB1, promoting deubiquitination of RPTOR. Phosphorylates caspase CASP8 at 'Tyr-380' which negatively regulates CASP8 processing and activation, down-regulating CASP8 proapoptotic function. Mediates laminin-induced activation of RAC1 signaling through phosphorylation of syntrophin (By similarity). [Isoform 1]: Non-receptor protein tyrosine kinase which phosphorylates synaptophysin with high affinity. [Isoform 2]: Non-receptor protein tyrosine kinase which shows higher basal kinase activity than isoform 1, possibly due to weakened intramolecular interactions which enhance autophosphorylation of Tyr-419 and subsequent activation (By similarity). The SH3 domain shows reduced affinity with the linker sequence between the SH2 and kinase domains which may account for the increased basal activity (By similarity). Displays altered substrate specificity compared to isoform 1, showing weak affinity for synaptophysin and for peptide substrates containing class I or class II SH3 domain-binding motifs (By similarity). Plays a role in L1CAM-mediated neurite elongation, possibly by acting downstream of L1CAM to drive cytoskeletal rearrangements involved in neurite outgrowth (By similarity). [Isoform 3]: Non-receptor protein tyrosine kinase which shows higher basal kinase activity than isoform 1, possibly due to weakened intramolecular interactions which enhance autophosphorylation of Tyr-419 and subsequent activation (By similarity). The SH3 domain shows reduced affinity with the linker sequence between the SH2 and kinase domains which may account for the increased basal activity (By similarity). Displays altered substrate specificity compared to isoform 1, showing weak affinity for synaptophysin and for peptide substrates containing class I or class II SH3 domain-binding motifs (By similarity). Plays a role in neurite elongation (By similarity).
Synonyms: p60-Src; SRC1; ASV; c-src; THC6
Tractability: Small molecule: an approved drug acts on it; a structure with a bound ligand is known; a high-quality ligand is known; it has a high-quality binding pocket; it belongs to a druggable protein family. Antibody: UniProt places it where antibodies can reach, with high confidence; its Gene Ontology location is reachable by antibodies, with high confidence; the Human Protein Atlas places it where antibodies can reach. PROTAC: it is named in the literature on targeted protein degradation; UniProt records ubiquitination sites on it; ubiquitination databases record sites on it; its protein half-life has been measured; a small molecule that binds it is known.
Target class: Kinase; TK protein kinase group; Enzyme; Protein Kinase; Tyrosine protein kinase Src family
Chemical probes: CHEMBL170984, CHEMBL173453, DGY-06-116 (high quality), PD-0173958, PD-0179483, PD070153, PD080726, PD080759, PD081017, PD081097, PD081233, PD081245, PD081529, PD081821, PD081889, PD082057, PD082100, PD082225, PD082389, PD082462, and 34 more
Safety:
Unwanted effects reported when the protein is acted on. In parentheses: how it was acted on, where the effect was seen, and who reports it.
Abnormal behaviour (activation; central nervous system; source: Brennan et al. (2024))
anxiety (activation; central nervous system; source: Brennan et al. (2024))
bone disorder (inhibition; bone; source: Brennan et al. (2024))
cell hypertrophy (inhibition; source: Brennan et al. (2024))
cognitive disorder (activation; central nervous system; source: Brennan et al. (2024))
deep vein thrombosis (activation; cardiovascular; source: Brennan et al. (2024))
platelet dysfunction (inhibition; blood/bone marrow; source: Brennan et al. (2024))
Pleural effusion (inhibition; respiratory; source: Brennan et al. (2024))
pulmonary arterial hypertension (inhibition; cardiovascular; source: Brennan et al. (2024))
pulmonary oedema (activation; respiratory; source: Brennan et al. (2024))
thrombocytopenia (activation; blood; source: Brennan et al. (2024))
Gene: Protein-coding gene on chromosome 20 (37,344,673 to 37,406,050, forward strand). Ensembl gene ENSG00000197122.
Subcellular location: Cell membrane; Mitochondrion inner membrane; Nucleus; Cytoplasm, cytoskeleton; Cytoplasm, perinuclear region; Cell junction, focal adhesion; Cell junction
Subcellular location (Human Protein Atlas): Cell Junctions; Plasma membrane; Vesicles
Pathways (Reactome):
Signal Transduction: Activated NTRK2 signals through FYN; Activated NTRK3 signals through PI3K; Downregulation of ERBB4 signaling; Downstream signal transduction; Extra-nuclear estrogen signaling; G alpha (i) signalling events; G alpha (s) signalling events; GAB1 signalosome; GPER1 signaling; GRB2:SOS provides linkage to MAPK signaling for Integrins; Integrin signaling; MAP2K and MAPK activation; MET activates PTK2 signaling; Nuclear signaling by ERBB4; PI5P, PP2A and IER3 Regulate PI3K/AKT Signaling; PIP3 activates AKT signaling; RAF activation; RHO GTPases Activate Formins; RHOU GTPase cycle; Regulation of KIT signaling; Signaling by ALK; Signaling by EGFR; Signaling by ERBB2; Signaling by SCF-KIT; Spry regulation of FGF signaling; VEGFA-VEGFR2 Pathway; VEGFR2 mediated cell proliferation; p130Cas linkage to MAPK signaling for integrins; p38MAPK events
Developmental Biology: DCC mediated attractive signaling; EPH-Ephrin signaling; EPH-ephrin mediated repulsion of cells; EPHA-mediated growth cone collapse; EPHB-mediated forward signaling; Ephrin signaling; NCAM signaling for neurite out-growth; Netrin mediated repulsion signals; RET signaling; Recycling pathway of L1; Regulation of commissural axon pathfinding by SLIT and ROBO
and 30 more pathways
Gene Ontology:
Molecular function: BMP receptor binding; cadherin binding; enzyme binding; ephrin receptor binding; heme binding; integrin binding; non-membrane spanning protein tyrosine kinase activity; phospholipase activator activity; phospholipase binding; phosphoprotein binding; protein binding; protein kinase activity; protein tyrosine kinase activity; scaffold protein binding; SH2 domain binding; signaling receptor binding; transmembrane transporter binding; ATPase binding; ionotropic glutamate receptor binding; protein tyrosine kinase activator activity; signaling receptor activator activity; ATP binding; connexin binding; kinase activity; protein domain specific binding
Biological process: cellular response to reactive oxygen species; focal adhesion assembly; integrin-mediated signaling pathway; interleukin-6-mediated signaling pathway; intestinal epithelial cell development; intracellular signal transduction; negative regulation of anoikis; negative regulation of apoptotic process; negative regulation of extrinsic apoptotic signaling pathway; negative regulation of hippo signaling; negative regulation of intrinsic apoptotic signaling pathway; negative regulation of mitochondrial depolarization; negative regulation of neutrophil activation; negative regulation of protein-containing complex assembly; negative regulation of telomere maintenance; negative regulation of transcription by RNA polymerase II; peptidyl-tyrosine phosphorylation; positive regulation of dephosphorylation; positive regulation of epithelial cell migration; positive regulation of lamellipodium morphogenesis; positive regulation of Notch signaling pathway; positive regulation of phosphatidylinositol 3-kinase/protein kinase B signal transduction; positive regulation of small GTPase mediated signal transduction; positive regulation of TORC1 signaling; regulation of caveolin-mediated endocytosis; and 41 more
Cellular component: anchoring junction; caveola; cell junction; cell-cell junction; cytoplasm; cytosol; extracellular exosome; late endosome; lysosome; mitochondrial inner membrane; mitochondrion; nucleus; perinuclear region of cytoplasm; plasma membrane; focal adhesion; membrane raft; actin filament; cytoskeleton; membrane; podosome; ruffle membrane
Genetic constraint (gnomAD): Loss-of-function variants: 13 observed, 53.91 expected, observed/expected ratio (o/e) 0.24, 90% interval 0.16 to 0.38. The upper end of that interval is the gene's LOEUF score, 0.38, which puts it in group 1 of 6, group 1 being the genes least tolerant of losing a copy. Missense variants: 436 observed, 633.01 expected, observed/expected ratio (o/e) 0.69, 90% interval 0.64 to 0.75. Synonymous variants: 280 observed, 267.77 expected, observed/expected ratio (o/e) 1.05, 90% interval 0.95 to 1.15.
Gene-disease validity (ClinGen):
ClinGen rates the evidence that SRC causes each of these diseases.
thrombocytopenia 6 (autosomal dominant): Moderate.
Cancer hallmarks: tumour promoting inflammation; invasion and metastasis (promotes); genome instability and mutations (suppresses); proliferative signalling (promotes); change of cellular energetics (promotes); escaping immune response to cancer; angiogenesis (promotes); escaping programmed cell death; genome instability and mutations
Homologues: Orthologues: chimpanzee SRC (100% identical), macaque SRC (99% identical), dog SRC (99% identical), mouse Src (99% identical), pig SRC (99% identical), guinea pig SRC (98% identical), rabbit SRC (94% identical), tropical clawed frog src (88% identical), zebrafish src (83% identical), rat Src (82% identical). Paralogues in human: YES1 (76% identical), FYN (69% identical), FGR (66% identical), HCK (54% identical), BLK (52% identical), LYN (52% identical), LCK (51% identical), FRK (45% identical), ABL2 (40% identical), ABL1 (39% identical), PTK6 (38% identical), SRMS (37% identical), and 20 more.
Diseases named in the same sentence as SRC in open-access papers:
SRC is named in the same sentence as 336 diseases in open-access papers, as found by Europe PMC text mining. Sharing a sentence is not in itself a finding about the gene and the disease. The quoted sentences say what the papers report.
breast cancer (332 papers, 2005 to 2026). A primary or metastatic malignant neoplasm involving the breast. "In breast cancer, the oncogene SRC encodes the tyrosine kinase Src that phosphorylates the tyrosine 20 residue in the cytoplasmic region of TfR1 and potentiates breast cancer cell survival and inhibits apoptosis." (PMID 33815364, 2021). "It is reported that metastatic breast cancer cells that lodge in the bone marrow become addicted to SRC signaling, what would make them highly susceptible to eCF506 treatment." (PMID 34417202, 2021). "The abnormally activated FAK and SRC proteins are associated with the progression of several types of tumors, including colon cancer, breast cancer, prostate cancer, lung cancer and oral cancer." (PMID 33240810, 2020). "We found that genetic variants in RPS6KA1, ATF6B, CREB3L1 and SRC genes were associated with modified relationships between reproductive factors and breast cancer, especially the protective effect of the number of deliveries and the early age at menopause." (PMID 29530003, 2018). "Overall, these observations identified SRC as a molecule of choice for targeting EPHB6-deficient breast cancer cells." (PMID 27418135, 2016). "In breast cancer, elevated SRC expression is associated with poor prognosis." (PMID 36016606, 2022). "Besides being active during hypoxia, SRC activation has been found to promote invasiveness and motility of cancer cells in response to radiotherapy; in breast cancer cells it has been shown that fractional irradiation caused an increase in SRC phosphorylation." (PMID 33020459, 2020). "SRC activity has previously been linked to resistance to anti-HER2 therapies, with SRC activation correlating with trastuzumab resistance in breast cancer cells, and overexpression of an activated mutant form of SRC (Y527F) resulted in resistance to trastuzumab-mediated growth inhibition." (PMID 29435137, 2018). "SRC has formerly been implicated in metastatic dissemination in breast cancer." (PMID 29032615, 2017). "EGFR/MET complex associated with SRC were reported in EGFR TKI-resistant breast cancer cells." (PMID 24714091, 2014). "Likewise, the 'SRC' and 'B-catenin' pathways are known to be co-regulated in breast cancer and associated with poor survival." (PMID 19327144, 2009). "As the reasons behind this selectivity could be beneficial for the treatment of SRC-associated pathologies, we set to investigate the mode of binding of eCF506 to SRC and the molecular phenotype of eCF506-treated breast cancer cells compared with clinical SRC/ABL inhibitors." (PMID 34417202, 2021). "This methodology has been effective in uncovering optimal drug targets in various contexts, including previously established targets for breast cancer (e.g., SRC, MTOR) and spinal cord injury (e.g., TNF, FOS, IL6)." (PMID 40895536, 2025). "YAP can be directly phosphorylated and activated by active SRC in intestine epithelial cells and breast cancer cells." (PMID 37950040, 2024). "A semi-quantitative comparison via western blot was, however, done in breast cancer cell lines, revealing similar amounts of pSRC and SRC in the respective unstimulated control samples." (PMID 38847867, 2024). "BCAR3’s overexpression in breast cancer cells notably boosts ERK1/2 activation through c-SRC, with phosphorylation markers indicating enhanced activity." (PMID 38730626, 2024). "In one study, advanced breast cancer patients with bone metastases were recruited, with ‘SRC responsiveness’ gene signatures (derived from cell line studies) and were treated with Dasatinib, but only one experienced a clinical benefit." (PMID 39327614, 2024). "Favouring signalling via this mechanism, lipid rafts have been shown to provide a platform for EGFR and c-SRC interaction in breast cancer cells." (PMID 39165974, 2024). "In breast cancer, silencing ClpP decreases the activity of SRC and AKT and phosphorylation of PI3K, thereby interfering with the proliferation, migration and apoptosis of breast cancer cells." (PMID 39261452, 2024).